TLR2 (toll like receptor 2)
Diseases named in the same sentence as TLR2 in open-access papers (continued):
Sharing a sentence is not in itself a finding about the gene and the disease.
atherosclerosis (137 papers, 2008 to 2026). A disease characterized by the build-up of fatty material and calcium deposition in the arterial wall resulting in partial or complete occlusion of the arterial lumen. "TLR2 is one of the receptors that can bind to oxidized LDL in atherosclerosis, and deficiency of this receptor in mice has been shown to have a protective effect on atherosclerosis." (PMID 39392102, 2024). "Recent studies have indicated that TLR2 is actively involved in atherosclerosis caused by Chlamydia pneumoniae, Porphyromonas gingivalis and Helicobacter pylori." (PMID 35509837, 2022). "Our study also found that new genes like CSF2RB, IL1RN, CCL5, MMP9, CD53, NCF2 and TLR2 associated with Inflammation present high expression both in psoriasis and atherosclerosis." (PMID 34122426, 2021). "TLR2 are pattern recognition receptors of innate immunity that are highly expressed in endothelial cells placed at regions of susceptibility to atherosclerosis, such as the aortic arch." (PMID 34804419, 2021). "Frank and his colleagues reported that P. gingivalis demands TLR2 to induce oral inflammatory bone loss in mice, and P. gingivalis infection promotes atherosclerosis in hyperlipidemia mice with increased expression of TLR2 and TLR4." (PMID 32002588, 2020). "In ApoE(+/−) mice, for example, the genetic deficiency in TLR2 reduced diet-and/or pathogen-associated atherosclerosis." (PMID 32650372, 2020). "Pg has also been show to act through TLR2 engagement, and TLR2-mediated effects are reported to be important in alveolar bone loss in periodontal disease and atherosclerosis." (PMID 29329335, 2018). "It has been postulated that the association between microbial infection and atherosclerosis involves common mechanisms of signaling via TLR2 and TLR4." (PMID 28348558, 2017). "TLR2 activation has been implicated in atherosclerosis but the role of TLRs on the vulnerability of plaque/remodeling of the lesion remains uncertain." (PMID 28257481, 2017). "Genetic deficiency of TLR2 reduces diet-induced atherosclerosis in ApoE+/− mice, and TLR2 expression and activation regulates the inflammatory processes and ROS production following vascular injury in mouse models." (PMID 27795867, 2016). "This study showed that endothelial TLR2 expression is linked to early atherosclerosis in murine models." (PMID 27795867, 2016). "Atherosclerosis development in murine models has largely been shown to be associated with increased expression of TLR-2 and TLR-4." (PMID 26101539, 2015). "We have demonstrated that P. gingivalis-induced oral inflammatory bone loss and acceleration of systemic inflammation and atherosclerosis is dependent on TLR2 signaling." (PMID 25010102, 2014). "Work carried out by Madan and Amar revealed that TLR2 mediates diet and/or pathogen associated atherosclerosis." (PMID 23880853, 2013). "TLR2 has also been implicated in other inflammatory diseases such as atherosclerosis and inflammatory bowel disease." (PMID 21345222, 2011). "Here we report an assessment of the role of the TLR2 pathway in atherosclerosis associated with a high-fat diet and/or bacteria in ApoE+/− mice." (PMID 18787704, 2008). "We performed cytokine profiling in order to further investigate the systemic inflammatory status associated with TLR2 deficiency and the involvement of TLR2 in atherosclerosis." (PMID 18787704, 2008). "Indeed, overexpression of TLR2 in mice leads to early atherosclerosis onset, whilst TLR2-deficient mice display reduced atherosclerosis-associated inflammation." (PMID 40076974, 2025).
atherosclerosis (continued). "Collected evidence suggested that Zym stimulates the immune system by activation of TLR2, and vascular inflammation in atherosclerosis is associated with the activation of Zym-induced TLR2 signaling pathways which then transfer transmembrane signals that activate nuclear factor-kappa B (NF-ƙB)." (PMID 34804419, 2021). "However, PRRs on endothelial cells, including TLR4 and TLR2, have also been associated with vascular inflammation and cardiovascular disease, such as atherosclerosis." (PMID 24690886, 2014). "Also deficiency of TLR-2 has been associated with lowered diet- and pathogen induced atherosclerosis in mouse models." (PMID 24498948, 2013). "Indeed, mice deficient in TLR4, TLR2 and MyD88 all have reduced atherosclerosis which establishes that TLR-dependent pathways contribute to disease development." (PMID 18787704, 2008). "It was initially found that S1P selectively attenuates TLR2 signaling, such as transcriptional activity driven by NF-κB signaling, and negative crosstalk between S1PRs and TLR2 signaling may be associated with the atherosclerosis protective effect of S1P." (PMID 38482014, 2024). "Bacterial LPS were shown to activate proinflammatory production of matrix metalloproteinase (MMP)-9 through TLR2/4 activation in macrophages, VSMCs, and endothelial cells that could lead to the atherosclerosis-associated vascular remodeling and plaque destabilization." (PMID 26175728, 2015). "That bacterial PDHC lipids are known to engage TLR2 in promoting cell activation of dendritic cells, macrophages or osteoblasts and are prevalent even in patent artery segments, raises the possibility that bacterial lipid deposition predisposes major arteries to the development of atherosclerosis." (PMID 21347306, 2011). "Thus, increased level of gelsolin seen in ApoE+/−-TLR2+/+ mice fed a high fat diet and injected with P. g may be linked to the increased apoptosis and atherosclerosis observed in this group." (PMID 18787704, 2008). "Another study showed that blocking TLR2/CXCR4 can significantly delay or perhaps even reverse atherosclerosis induced by Chlamydia pneumoniae infection." (PMID 40535169, 2025). "Dehydrocostus lactone alleviates atherosclerosis by promoting cholesterol efflux and inhibiting inflammation via the TLR2/PPAR-γ/NF-κB signaling pathway in both in vivo and in vitro models." (PMID 41158126, 2025). "This study demonstrates that treatment with DHL alleviates atherosclerosis by promoting cholesterol efflux and inhibiting inflammation through the TLR2/PPAR-γ/NF-κB signaling pathway." (PMID 40537740, 2025). "Blocking CXCR4 can promote autophagy in macrophages, alleviate atherosclerosis, improve myocardial structure, reduce the severity of coronary artery disease, and reverse atherosclerosis induced by Chlamydia pneumoniae infection by blocking TLR2/CXCR4." (PMID 40535169, 2025). "Beyond colitis and osteoarthritis, ALD and dehydrocostus lactone alleviate atherosclerosis by promoting cholesterol efflux in macrophage-derived foam cells and modulating the TLR2/PPAR-γ/NF-κB pathway." (PMID 41158126, 2025).
atherosclerosis (continued). "Toll-like receptor 2 (TLR2)-mediated NF-κB activation induces VC in atherosclerosis by activating p38 and ERK1/2 signaling and inhibiting osteoprotegerin (OPG) expression." (PMID 39834821, 2024). "It is known that the symbiotic Segmented Filamentous Bacteria in the gut and oral cavity are involved in the pathogenesis of TLR2-dependent atherosclerosis through serine dipeptide lipid deposition and arterial wall metabolism." (PMID 38622667, 2024). "During the late stages of atherosclerosis, anthocyanins reduce the expression of Toll-like receptor 2 (TLR2) signaling in endothelial cells that regulate the neutrophil stimulation of stress and endothelial cell apoptosis." (PMID 38540758, 2024). "To further explore the in vivo role of TLR2 in inducing SMCs apoptosis and miR-143/145 expression during P. gingivalis-accelerated atherosclerosis, we constructed a P. gingivalis-infected TLR2−/−ApoE−/− mouse model." (PMID 37380627, 2023). "This study successfully identified key genes associated with EndMT-related atherosclerosis, such as CD68, TLR2, MYD88, IRF7, STAT1, and IL1B, all of which demonstrate substantial diagnostic potential for detecting atherosclerotic plaques." (PMID 38268851, 2023). "By constructing three genetic mouse models, we further confirm the in vivo roles of TLR2 and miR-143/145 in P. gingivalis-accelerated atherosclerosis." (PMID 37380627, 2023). "Platelet hyperreactivity and thrombosis are critical for dyslipidemia-induced atherosclerosis dependent on toll-like receptor 2- (TLR2-) mediated inflammatory signaling." (PMID 36158875, 2022). "TLR2 was found to promote vascular smooth muscle cell chondrogenic differentiation and consequent calcification in atherosclerosis by activating p38 and extracellular regulated protein kinases (ERK) 1/2 signaling." (PMID 35873459, 2022). "The Toll-like receptor TLR2, which is known to be involved in atherosclerosis, was upregulated by CVD." (PMID 36045343, 2022). "The related TLR2 genes were primarily enriched in the pathways of atherosclerosis, arteriosclerotic cardiovascular disease, and arteriosclerosis, suggesting the clinical role of TLR2 in the progression of MI." (PMID 35840880, 2022). "As data regarding the bioactivities of bacterial glycine lipids are limited, it is helpful to compare their effects to other TLR2 agonists in the context of lipid metabolism and atherosclerosis." (PMID 35278409, 2022). "Atherosclerosis is a multifactorial disease with different stages of inflammation from initiation to progression, and toll-like receptors (TLRs), notably TLR2 and TLR4, are involved in developing the atherosclerotic disease." (PMID 35928361, 2022). "Many studies have shown that patients with atherosclerosis increased the expression of TLR2 in atherosclerotic aorta." (PMID 34901005, 2021). "Our findings indicate that 5-MTP is a vascular arsenal against atherosclerosis and calcification by preventing TLR2–mediated SMC phenotypic switch to chondrocytes and the consequent calcification." (PMID 34749728, 2021). "NETs license macrophages to turn on transcriptional regulation of IL-6 and pro-IL-1β via TLR2/4 in atherosclerosis." (PMID 34250033, 2021). "The results show that vascular production of 5-MTP was suppressed by HFD-induced atherosclerosis in ApoE−/− mice, which was restored by genetic deletion of TLR2." (PMID 34749728, 2021). "Further evidence supporting the roles of TLR2 and TLR4 in atherosclerosis is the fact that TLR2 and TLR4 agonists can stimulate atherosclerosis in various mouse models." (PMID 32378144, 2021). "There is growing evidence that TLR2 is the major initiator of inflammation and promotes atherosclerosis." (PMID 34804419, 2021). "It is possible that TLR2/4 activation suppress TPH-1 expression at the transcriptional level in HFD-induced atherosclerosis." (PMID 34749728, 2021).
atherosclerosis (continued). "This study identified that rSj-Cys stimulated Treg and M2 macrophages to secrete regulatory cytokines IL-10 and TGF-β that inhibit oxidized lipid-induced inflammation and atherosclerosis through inhibiting the TLR2/Myd88 pathway." (PMID 34901005, 2021). "These mediators damage human coronary smooth muscle cells and increase atherosclerosis which was found to be TLR2- and TLR4-dependent." (PMID 33679711, 2020). "Overall, activation of TLR2 and 4 seems to have a profound impact on infection-related atherosclerosis." (PMID 32002588, 2020). "Mice with a deficiency of TLR2 and TLR4 or downstream signaling proteins (i.e., IRAK4, TRAF6, TRIF, or MYD88) shows protection from atherosclerosis and various models of heart failure." (PMID 32664594, 2020). "Other studies showed that TLR2 expression is enhanced in patients with diabetes, and TLR2/TLR4 stimuli promote inflammation in obese patients with atherosclerosis." (PMID 32714475, 2020). "Numerous studies have reported that many TLRs, including TLR2, are involved in the pathogenesis of CVDs, including atherosclerosis." (PMID 32650372, 2020). "While given that TLR2 promotes immune-mediated plaque instability, atherosclerosis and exerts pro-thrombotic abilities, this would suggest a regimented chain of events leading to ACS rather than an acute event." (PMID 31644579, 2019). "The lipid rafts have been shown to play an essential role in TLR2/4 signaling pathway and atherosclerosis progression." (PMID 31366948, 2019). "A recent study reported that TLR2 and TLR4 deficiency markedly reduced atherosclerosis that was induced by oral bacteria." (PMID 31583048, 2019). "In the condition of oxidative stress, as well as in aging, hyperlipidemia, atherosclerosis, and stroke, Toll-like receptor-2/3/4/6 (TLR-2/3/4/6) are up-regulated or activated." (PMID 30505270, 2018). "In human atheroma cell cultures blockade of TLR2 and MyD88 inhibits NF-κB activation and matrix metalloproteinase (MMP) production, suggesting that MyD88-mediated TLR2 signaling contributes to human atherosclerosis." (PMID 30225265, 2018). "This review article aims to describe the immunological role of TLRs in promoting the development of atherosclerosis, with a primary focus on the function of TLR2, TLR4, and TLR9." (PMID 27795867, 2016). "The atherogenic role of these signaling molecules is supported by observations in ApoE-null mice deficient for TLR2, TLR4, or MyD88 that have attenuated atherosclerosis." (PMID 26175728, 2015). "While TLR2 has been shown to be pro-atherogenic in a mouse model of PD and atherosclerosis, TLR4 reduces lesion burden." (PMID 25938460, 2015). "We now know the innate immune receptors, TLR4 and TLR2, intrinsically regulate atherosclerosis in animal models and induce inflammatory responses in human vascular cells." (PMID 24690886, 2014). "A role for TLRs in high-fat-diet-induced atherosclerosis in animal models has been shown in studies using ApoE-/- TLR2-/- and ApoE-/- TLR4-/- mice." (PMID 25540039, 2014). "Accordingly, mRNA expression of TLR-2 and TLR-4 in the aorta is associated with the severity of atherosclerosis and serum levels of inflammatory markers in hypercholesterolemic rabbits." (PMID 24901254, 2014). "In humans, studies of atheroma cell cultures revealed that blockade of TLR2 and MyD88 inhibits NF-κB activation and matrix metalloproteinase (MMP) production, suggesting that MyD88-mediated TLR2 signalling contributes to human atherosclerosis." (PMID 23880853, 2013). "In contrast to previous studies on TLR2, when ApoE−/− mice deficient in TLR4 were infected with P. gingivalis they were paradoxically more susceptible for developing atherosclerosis, presenting with increased levels of inflammatory Th17 cells." (PMID 23880853, 2013).
atherosclerosis (continued). "During atherosclerosis, these mechanisms can be detrimental, as seen by the activation of TLR2 and TLR4." (PMID 23880853, 2013). "For example, neither the presence of circulating mediators of inflammation or aortic expression of TLR2 and 4 correlate with atherosclerosis in W83 infected animals." (PMID 23300720, 2012). "In atherosclerosis models, TLR2 activation of monocytes resulted in an increase in adhesive and migratory capacity of cells." (PMID 21858161, 2011). "The circulating monocytes of ApoE-/- mice with advanced atherosclerosis have increased TLR2 and TLR4 expression." (PMID 21526997, 2011). "TLRs are differentially expressed by the various cell types in atherosclerosis, with TLR2 and TLR4 found on monocytes, macrophages, foam cells and myeloid DCs, as well as smooth muscle cells and B lymphocytes." (PMID 21526997, 2011). "In a hypercholesterolaemic rabbit model of atherosclerosis, carotid artery liposomal transfection of TLR2 and TLR4 cDNA revealed that upregulation of either TLR alone did not significantly affect carotid atherosclerosis." (PMID 21526997, 2011). "So far, it appears that TLR-2 and -4 activation has profound consequences on the recruitment of monocytes and foam cell formation in murine models of atherosclerosis." (PMID 20652007, 2010). "Antagonism of TLR-2 or TLR-4 signalling is currently perceived as the most attractive target for development of therapeutics for the treatment of atherosclerosis." (PMID 20652007, 2010). "Our expression proteomic approach extends the growing body of literature linking TLR2 and atherogenesis by identifying proteins involved in P. g- and/or diet-induced atherosclerosis in ApoE+/− mice." (PMID 18787704, 2008). "Two important observations suggest TLR2 as a novel target to consider for therapeutic intervention in atherosclerosis." (PMID 18787704, 2008). "After establishing the involvement of TLR2 in diet/bacteria induced atherosclerosis, we performed a detailed examination of plaque compositions by immunofluorescence staining." (PMID 18787704, 2008). "Taken together, our results confirm the important role for TLR2 signaling in diet and/or bacteria enhanced atherosclerosis in an ApoE+/− mouse model, providing a link between innate immunity, inflammation and atherosclerosis." (PMID 18787704, 2008). "Stimulation by the specific agonist FSL-1 was used to further establish the role of TLR2 in modulating the progression of diet and/or bacteria enhanced atherosclerosis in mice with normal expression of TLR2." (PMID 18787704, 2008). "To further establish the role of TLR2 in modulating the progression of atherosclerosis, we stimulated mice with the TLR2 agonist known as FSL-1." (PMID 18787704, 2008). "Additionally, blocking TLR2/CXCR4 can significantly delay or even nearly reverse atherosclerosis induced by Chlamydia pneumoniae infection." (PMID 40535169, 2025). "Hypertriglyceridemia enriched with apolipoproteins C-III, could activate toll-like receptor 2 and NF-kB inflammatory signaling pathways, leading to development of atherosclerosis." (PMID 40166678, 2025). "Furthermore, studies have shown that TLR-2 plays a significant role in driving inflammation in human atherosclerosis through a signaling adaptor called MyD88." (PMID 38002294, 2023). "Whether TLR2/mtROS/JunB-Fra-1/MMP2 signal axis participates in C. pneumoniae infection-induced atherosclerosis development remains unknown." (PMID 35493076, 2022). "Despite evidence suggesting that L654 and other glycine lipids activate TLR2 signaling, we report here protective effects against hepatic inflammation and atherosclerosis with chronic exposure, particularly in HFD conditions where fecal and serum glycine lipids are reduced." (PMID 35278409, 2022).